CCR7 (C-C motif chemokine receptor 7)
Diseases named in the same sentence as CCR7 in open-access papers (continued):
Sharing a sentence is not in itself a finding about the gene and the disease.
cancer (continued). "Our findings suggest that the CCL21/CCR7 axis, BTLA, TME, EMT, and adhesion may be key regulators of cancer chemoprevention in C57BL/6J mice receiving allogenic and orthotopic transplants of KMPC44 cells by Fx administration." (PMID 34948416, 2021). "In contrast, CCR7 expression levels on the surface of cancer cells have not yet been sufficiently analysed to make statistically unbiased conclusions regarding correlations with cancer outcomes." (PMID 34685420, 2021). "In both homeostasis and cancer, CCR7 but not other receptors, specifically drives cell homing into LN and other secondary lymphoid organs (SLO)." (PMID 33841445, 2021). "Cancer-specific Tscm or Tcm cells, which express CD27, CCR7, and CD62L molecules, may be the most clinically relevant subtypes for successful T cell-based immunotherapy." (PMID 34603332, 2021). "Slug can also regulate the C-X-C Motif Chemokine Receptor 4 (CXCR4) and C-C chemokine receptor type 7 (CCR7) proteins, related to chemokines that are overexpressed in several types of cancer, including HNSCCs, and, similarly to Twist, can induce cervical lymph node metastasis." (PMID 34204259, 2021). "Neutrophils marker genes C-C motif chemokine receptor 7 (CCR7) and CD11b, were favorably linked to STAT3 in cancer, except for CCR7 showing a negative correlation with STAT3 in BLCA." (PMID 32486001, 2020). "Since SH3PXD2A or CCR7 are reported to be involved cancer cell invasion and migration, downregulation of CTCF targets SH3PXD2A and CCR7 by SH3PXD2A-AS1 might have similar functional effects on trophoblast cells during placentation." (PMID 32719429, 2020). "The downregulation of let-7a-5p may be related to barrier abnormalities by targeting ribonucleotide reductase regulatory subunit M2 (RRM2) and C-C motif chemokine receptor 7 (CCR7), which are mainly involved in cancer cell proliferation." (PMID 32806619, 2020). "By introducing interstitial flows of just 0.2 μm/s through the 3D ECM in the absence of LECs, cancer cell migration was enhanced via autologous CCR7 signaling." (PMID 32002106, 2020). "Taken together, the production of IGF-1 and the activation of expression of CCR7 result in lymphangiogenesis and may promote cell migration toward lymph node in middle stage LSCC, suggesting that cancer cells may metastasize through lymph node in LSCC." (PMID 31217907, 2019). "PDAC tumors have a subset of highly overexpressed (and highly expressed in terms of magnitude) chemokine receptors (CCR6, CCR7, CXCR3 and CXCR4) not expressed in PDAC cancer cells but likely associated with immune cells and their activation." (PMID 31765370, 2019). "Furthermore the data also indicated the potential importance of developing therapeutic strategies targeting cancer stem-like cells and CCL21/CCR7 for reducing metastasis." (PMID 27505247, 2016). "IL-1β did not regulate CCR6 or CCR7, two other CC chemokine receptors related to cancer metastasis, in either Tca8113 or Hep2 cells." (PMID 26176534, 2015). "Similar to cancer cells, studies have suggested that IPF lung fibroblasts might utilize CCR7 for migration into the lungs, proliferation and survival." (PMID 24478703, 2014). "Furthermore, the patients with a higher CCR7 and VEGF-C expression in their cancer cells had significantly higher incidences of lymphatic metastasis (P<0.01)." (PMID 23761820, 2013). "Based on this, developing molecular target therapy against CCR7 and FOXP3 might be a promising strategy for cancer treatment." (PMID 24040244, 2013). "As hypothesized, the expression levels of CCR7 and CCL21 were significantly increased in cancer cells and cancerous tissues from patients." (PMID 22251626, 2012). "CCR7 is highly expressed in non-small cell lung cancer (NSCLC), breast cancer, and squamous cell carcinoma of the head and neck and is responsible for mediating metastasis in certain cancer cells lines." (PMID 21698152, 2011).
cancer (continued). "In the first scenario, MDI (which consisted of a total dose of 10 Gy in five daily fractions) led to reduced mRNA expression of some proinflammatory markers (such as CCR7 and IL1β), with no changes documented for anti-inflammatory markers, while cancer cell invasion and migration were promoted." (PMID 37347290, 2023). "However, CCR7 expression is not restricted to leukocytes but can be induced by certain cancer cells, which then follow the CCL19/CCL21 guidance cues to metastasize to lymphoid organs." (PMID 35563750, 2022). "This poses a quandary when considering antagonizing CCR7 as potential anti-cancer therapy, although specific targeting of CCR7 may be possible that does not adversely affect immune responses." (PMID 35203305, 2022). "In the process of module analysis and characteristic molecular screening, we selected two characteristic modules and 10 characteristic molecules (PTPRC, CD2, CD69, IRF8, CCR7, CCL5, il2rb, CXCL10, CCR5, TBX21), which could be used as biomarkers of cancer stem-like cells for GIST patients." (PMID 34925310, 2021). "However, the chemokines and their receptors that particularly stimulate tumorigenesis, including CCR7, CXCL1, CXCL8, and CXCL12/CXCR4, could, consequently, act as poor prognostic markers for cancer patients." (PMID 31991604, 2020). "Chemokine (C-C motif) receptor 7 (CCR7), a class A subtype G-Protein Coupled Receptor (GPCR), is involved in the migration, activation and survival of multiple cell types including dendritic cells, T cells, eosinophils, B cells, endothelial cells and different cancer cells." (PMID 26504105, 2015). "Supposedly, a ligand of CCR7 is secreted by the cancer cells themselves and allows the cancer cells to migrate to the lymphoid tissues; thus, blocking CCR7 in cancer cells could inhibit metastasis without the immune cell responses." (PMID 22251626, 2012). "Indeed, despite an upregulation of CCR7 even higher than gold standard DC, alternative DC displayed a reduced migration in vitro toward its ligand CCL21 and would then have poor migration to the lymph node upon subcutaneous or intradermal injection into cancer patients." (PMID 26695182, 2015). "Thus, whether CCR7 expression or not and the level of its expression may directly affect cancer metastasis and prognosis." (PMID 24040244, 2013). "The expression levels of CCR7, CXCR4 and VEGF-C in the cancer cells were all significantly higher than those in the non-cancerous regions (P<0.05)." (PMID 23761820, 2013). "Interestingly, when macrophages were cocultured with radioresistant cells, both proinflammatory (CCR7, CD80) and anti-inflammatory markers (IL-10 and CCL18) were overexpressed, with no changes in cancer cell migration and invasion." (PMID 37347290, 2023). "The discovery that cancer cells overexpress C-C Chemokine receptor 7 (CCR7), which directs them to organs that express their ligands CCL21 and CCL19, led to an increase in reports confirming that chemokine receptors were present in a non-random manner in many other cancers." (PMID 32340161, 2020).
infection (203 papers, 2009 to 2026). The state of being infected such as from the introduction of a foreign agent such as serum, vaccine, antigenic substance or organism. "Right: Plot showing higher levels of expression of the HIV co-receptor CCR5 on CCR7- Tm cells, which provides an explanation for the higher susceptibility of these cells to infection." (PMID 32452381, 2020). "Increased levels of CCR5 and CCR7 documented a massive influx of mDCs to both LNs and mucosal tissues in the pathogenic infection of PTMs." (PMID 24098110, 2013). "Although CCR7-deficient mice displayed reduced T-cell priming after infection with lymphocytic choriomeningitis virus or Listeria monocytogenes, mice were able to generate sufficient immune responses." (PMID 22533989, 2012). "The infection of macrophages by T. gondii tachyzoites (type I) initiates a migratory activation, which encompasses the expression of DC-associated transcription factors, phenotypical changes, and the onset of CCR7-dependent chemotaxis." (PMID 39207098, 2024). "Our data indicate that the CCR7-deficient infection model may be beneficial to address other mechanisms of susceptibility and resistance to L. major infection, such as the wound healing response." (PMID 24205367, 2013). "The observed lower expression of T cell associated genes (e.g. IL7R, CD3E, CCR7 and PTPRCv1) in TB patients has been shown previously and might be associated with reactivation of infection and migration of cells to the site of infection." (PMID 31821366, 2019). "Interestingly, in the i.d. model, CCR7 deficiency leads to a significant reduction of the spread of Brucella from the footpad lesion to the draining LN and the spleen at 1 and 3 days post infection, and an important increase in the number of bacteria in the cutaneous lesion at 7 and 14 days." (PMID 31354728, 2019). "Seven major T and natural killer (NK) cell clusters were identified, including a population resembling naïve, circulating CD4+ T cells (T cell CD4 Ccr7) that decreased in frequency as infection progressed in both mouse strains, albeit earlier in C57BL/6 mice." (PMID 40986319, 2025). "We found that CCR7 expression in lung DCs was decreased in the first 2 days of infection in geriatric cotton rats compared with adults." (PMID 39818970, 2025). "We discovered a novel PD-1+CD8+CD45RA+CCR7+ T lymphocyte subset in suitable donors that was significantly correlated with lower incidence of aGVHD and post-transplant anti-infection." (PMID 40175340, 2025). "The frequency of effector Tregs cluster 4 (CCR7+CTLA4+ICOS+CD38hi) was higher in HW+ Flores residents compared to the average of post-infection CHHIL time points (4 to 104 WPI) (P = 0.029) and decreased after deworming (P = 0.021)." (PMID 39013877, 2024). "In this context, it was demonstrated that Mtb-infected Mo-DCs recruited to the site of infection exhibit low CCR7 expression and impaired migration to lymph nodes compared to uninfected Mo-DCs." (PMID 38922679, 2024). "Collectively this data indicates that dual deletion of CCR2 and CCR7 strongly inhibits iMO recruitment to the brain during infection with either LACV or HSV-1." (PMID 38658802, 2024). "Prior studies have reported an increased expression of CCR7 in DCs following 24 h infection with Toxoplasma." (PMID 38977495, 2024). "Ccr7+Ido1+ DCs, Cd160+Cd8+ T cells, and Tnfrsf4+Cd4+ T cells all increased after infection, and were viral RNA-positive, suggesting direct involvement of these immunity hubs against SARS-CoV-2 infection." (PMID 39414763, 2024). "During the initial infection phase, γδ T cell activation and temporal accumulation in the splenic white pulp, alongside cDC1, occur via CCR7-signaling." (PMID 39211036, 2024). "We found a higher proportion of CCR7-bearing myeloid cells that had trafficked from the site of dermal infection to the spleen in MN compared to WN mice (p = 0.02)." (PMID 36630476, 2023).
infection (continued). "Three of these genes, S1PR1, GPR183, and CCR7, showed a trend of continuous downregulation throughout infection, with fold-changes of -1.68, -2.30, and -1.64 at D8, respectively." (PMID 37146079, 2023). "Conversely, a CD45RA+ CCR7- CD8+ (TEMRA) population gradually ascends, while the CD45RA- CCR7+ CD8+ central memory (TCM) cells remain stably low until day 240 post-infection." (PMID 37388738, 2023). "Human blood-derived CD1c+ mDCs are susceptible to infection with BCG, up-regulating CD40, CCR7, HLA-DR, CD86 and other maturation markers, as well as producing TNF-α and IL-6." (PMID 37475964, 2023). "Third, monocytes transferred to the site of intradermal infection in MN mice had diminished trafficking from infected skin to spleen when CCR7 was knocked-down or genetically ablated." (PMID 36630476, 2023). "Because of the high CCR7 expression, the central memory T cells reside in the secondary lymphoid organs and readily expand upon infection or booster vaccination." (PMID 35102140, 2022). "DPr1 signaling delays the migration of dendritic cells (DCs) to the lung and lymph nodes by down-regulating the expression of C-C chemokine receptor type 7 (CCR7) on respiratory DCs in response to infection." (PMID 36304162, 2022). "During active infection, the dendritic cells' expression of CCR7, a receptor for the chemokines CCL19 and CCL21, is increased." (PMID 35722038, 2022). "CCR7 was found to be an absolute requirement for protective immunity to T. gondii by enabling T cell priming and increasing IFN-γ production, while CCR7(−/−) mice succumbed to the parasite early in the acute phase of infection." (PMID 35177094, 2022). "The population of B lymphocytes expressing the chemokine receptor CCR7 decreased in those who previously had an infection with SARS-CoV-2." (PMID 36052060, 2022). "Vaccination after infection lead to expansion of spike-specific T cells and differentiation to CCR7(neg)CD45RA(pos) effectors." (PMID 36923729, 2022). "The analysis of the expression of these molecules revealed increased expression of Ccl25, Cxcl12 and P-selectin in the thymus, and decreased expression of Ccr7 in BM cells upon M. avium strain 25291 infection." (PMID 34987496, 2021). "In case of the homing markers, we were surprised to find an upregulation of CCR7 between 1.5 and 9 months post-infection." (PMID 34960178, 2021). "Considering HCMV-specific responses, only a part of HLA-A2pp65 and almost all anti-HCMV HLA-EUL40 CD8 T cells stained with HLA-EUL40 tetramers that persist in HCMV+ individuals post-infection display a CD45RA+ CCR7− phenotype and thus belong to TEMRA cells." (PMID 35008688, 2021). "We expected this marker to play a more dominant role during the acute phase of infection, as CCR7 is related to homing to secondary lymphoid organs, which most likely plays a role during T-cell priming." (PMID 34960178, 2021). "Infection rates inversely correlated with CCR7 expression levels, validating the PP-SLIDE prediction." (PMID 32452381, 2020). "We observed that RhCMV-specific CTLs were overwhelmingly (>90%) TEM2 (CD28– CCR7–), both before and during SIVmac239 infection." (PMID 32922404, 2020). "Third, infection of mDCs with HSV-1 and HSV-2 also leads to a downregulation of surface expression of the chemokine receptor CCR7 late during infection." (PMID 31963276, 2020). "In comparison, CCR7 is central for lymphocyte and dendritic cell functioning, including migration to tissues with active infection, and HMOX1 affects immune functions by controlling Heme metabolism." (PMID 33163005, 2020). "We also identify a number of host proteins that are upregulated by HIV during infection, including CCR7, CXCR5, and CD69." (PMID 32452381, 2020). "CCR7 silencing also increases the resistance to infection by increasing the number of neutrophils in the lung airways." (PMID 31545493, 2019).
infection (continued). "During WNV infections, CCR7+ DCs regulate the homing of T cells expressing the cognate ligands CCL19 or CCL21 into the lymph nodes immediately following infection and restrict leukocyte migration into the brain." (PMID 31632965, 2019). "Similar results were observed for the frequencies of CCR7+ DC subsets with the tendency of even more CCR7+CD4+ DCs upon infection with the PSM expressing WT strain." (PMID 31134074, 2019). "At 48 h post-infection, the number of CCR7+ mo-DCs increases, and the increase in cell number is accompanied by the significant activation of the COX-2-PGE2 signaling pathway in migrating DCs." (PMID 31632965, 2019). "Malaria infection also triggers the upregulation of CCR7 on pDCs, suggesting that homing to lymphoid tissues is enhanced during infection." (PMID 30886619, 2019). "In contrast, HRSV and HMPV infections induce less CCR7 expression and less efficient DC migration in response to CCL19 than HPIV3." (PMID 31632965, 2019). "In contrast, cDCs, specifically CD11b+ cDCs, in the MLN of developmentally exposed offspring had significantly reduced CCR7 levels 1 day after infection." (PMID 30412605, 2018). "In vitro chemotaxis experiments were performed with cells 3 days after infection to determine the respective effects of CCR7 and BTLA overexpression on imDC migration." (PMID 28393074, 2017). "Ccr5 and Cxcr3 expression was also lower in TB10.4-specific CD8+ T cells from perigonadal fat and Ccr7 remained unaffected after infection." (PMID 29040326, 2017). "The results revealed that the expression of CD11c, CD80, CD86, MHC class II, and CCR7 was increased 7 days post-infection." (PMID 27279150, 2016). "Quite different expression kinetics were observed for CXCR5, CCR5, and CCR7, which were elevated on the highest number of cells early during infection and decreased by 14, 30, and 60 days post infection." (PMID 27207308, 2016). "Binding of HIV gp120 to CXCR4 and CCL19 to its receptor CCR7 activate intracellular signalling that alters actin dynamics, facilitating nuclear localisation and infection of resting T-cells." (PMID 27383184, 2016). "In blood, infection led to a significant increase in T-effector cells (expressing the CD45RA−/CCR7+ phenotype) at the expense of Temra cells, a change that was not seen in the airway." (PMID 26687547, 2015). "A significantly lower absolute number of circulating CD8+CD45+CCR7+ cells (p = 0.002) was observed in P. vivax-infected individuals indicating that infection reduces the number of central memory T cells." (PMID 25636730, 2015). "Integrated and Gag HIV-DNA was detected at different levels in T-cell subsets of 5/5 subjects (CI on ART subjects 4, 6, 8, 12, and 16), with the infection of CD45RA+CCR7+ T-cells being inferior to that of memory CD45RA− T-cells." (PMID 25924895, 2015). "After both 4 and 8 hours of infection, many of the up-regulated genes were those that encode pro-inflammatory cytokines (IL-1α, IL-1β, IL-6 and TNF-α) and chemokines (CCR7 and IL-8), all of which have been implicated in RA and CVD pathogenesis." (PMID 24874661, 2014). "In agreement with previous studies, we found a majority of CXCR5high cells express CCR7, and it has previously been suggested that pTFH cells migrate to secondary lymphoid organs upon infection due their expression of CCR7 and CD62L." (PMID 24497824, 2014). "By contrast, effector memory cells have lost expression of CCR7, reside in the periphery and migrate to sites of infection." (PMID 24498312, 2014). "To investigate this further, we examined a panel of T cell activation markers (CD62L, CD69, CD44, CD25) and homing receptors (CCR5, CXCR3, CCR7) at days 5, 6 and 7 post-infection." (PMID 24809749, 2014). "Following MPXV infection, the frequency of CCR7+ CD56+ cells gradually decreased from 78% at day 0 to 50–60% on days 2–4 and to a low or negative frequency at days 7–8." (PMID 24147080, 2013).